SIRT1 (sirtuin 1)
Diseases named in the same sentence as SIRT1 in open-access papers (continued):
Sharing a sentence is not in itself a finding about the gene and the disease.
depression (continued). "For example, hippocampal sirtuin 1 (SIRT1) was reduced by loading chronic ultra-mild stress and repeated restraint stress, and pharmacologic and genetic inhibition of hippocampal SIRT1 function increased depression-like behaviors." (PMID 36835151, 2023). "This suggests that the downregulation of the SIRT1 expression in NAc contributes to the onset of depression." (PMID 37239191, 2023). "NLRP3 inflammasome underlies numerous debilitating disorders including depression, which elevates the expression of p65, NLRP3, ASC, cleaved IL-1β, cleaved gasdermin D, and caspase-1 and downregulates SIRT1." (PMID 37920216, 2023). "Sirt1 activation reduces the levels of pro-inflammatory cytokines, eventually leading to the amelioration of stress-induced neuroinflammation and depression-like behaviors in rodents." (PMID 37273278, 2023). "Our findings further highlight the potential of Sirt1 as a novel target for the treatment of anxiety and depression." (PMID 37273278, 2023). "Chronic stress decreases Sirt1 activity in the dentate gyrus, leading to elevated depression-like behaviors." (PMID 37124257, 2023). "At present, the research direction of the mechanism of exercise to improve SIRT1 expression in depression is gradually becoming clear, and exercise will increasingly prove to be an effective intervention and treatment." (PMID 37239191, 2023). "Our findings suggested that resveratrol can ameliorate inflammation and anxiety- and depression-like behaviors induced by maternal separation via the activation of the Sirt1/NF-κB pathway." (PMID 37273278, 2023). "Resveratrol ameliorated inflammation and anxiety- and depression-like behaviors induced by maternal separation by activating Sirt1 and thereby inhibiting the NF-κB signaling pathway." (PMID 37273278, 2023). "Another study including 12 000 Han Chinese women revealed 2 genes (SIRT1 and LHPP) to be significantly associated with severe depressive disorder." (PMID 38012695, 2023). "A genome-wide association study revealed an association between SIRT1 expression, a product of which is widely present in BLA, and the risk of major depressive disorder." (PMID 35625877, 2022). "BA has showed potential therapeutic effect for depression by reducing the levels of proinflammatory factor IL-1β possibly through regulation of SIRT1-NF-κB pathway in BV-2 microglia." (PMID 36408278, 2022). "The results indicated that SIRT1 was a mediator of S-ketamine in alleviating depression-like behavior." (PMID 35664490, 2022). "Some miRNAs in patients with depression involve single nucleotide polymorphisms (SNPs) and genetic variations, for example, SERT gene-associated miR-16 and SIRT1 gene-associated miR-134." (PMID 35562946, 2022). "and administration of RES directly into the nucleus accumbens also activates SIRT1 and produces a phenotype with increased anxiety and depression-like behaviour." (PMID 35554791, 2022). "Chronic social defeat stress, a model of depression in rodents, increases SIRT1 levels in the nucleus accumbens, a key brain reward region." (PMID 35875858, 2022). "Our previous studies have demonstrated that SIRT1 in the central nucleus of the amygdala (CeA) is involved in the development of chronic pain-related depression." (PMID 35959106, 2022). "The symptoms of depression in rats can be significantly improved by increasing the Sirt1 gene immune response in the hippocampus and hypothalamus following electric shock." (PMID 36177213, 2022). "The existing studies showed that SIRT1 expression in the serum obtained from patients with depression decreased compared with healthy people." (PMID 35664490, 2022). "Activation of the estrogen receptor alpha (ERα)/SIRT1/NF-κB pathway was involved in LPS-induced depression in aged female mice." (PMID 35935939, 2022). "Conversely, overexpression of miR-128-3p in CeA (P < 0.05) induced the depression-like behaviors and decreased SIRT1 levels in naïve rats, which were partially rescued following SIRT1 overexpression." (PMID 35959106, 2022).
depression (continued). "In terms of neuropsychiatric disorders, both SIRT1 and SIRT2 have been implicated in the epigenetic regulation of synaptic-plasticity related genes associated with depression and chronic stress; however, their exact roles remain controversial." (PMID 35936890, 2022). "The Sirt1 selective inhibitor EX-527 was employed to further study the mechanism of PAP-mediated depression." (PMID 35401226, 2022). "Several biomarker gene variants have been proposed for depression in different ethnic populations, including BICC1 rs9416742 in a UK population, SIRT1 rs12415800 in a Chinese Han population, and rs12462886 of a non-coding region in a US population." (PMID 35370858, 2022). "Meanwhile, SIRT1 activation in hippocampus blocked both the development of depression-related phenotypes and aberrant dendritic structures elicited by chronic stress exposure." (PMID 35664490, 2022). "Meanwhile, a positive relationship between SIRT1 and BDNF expression in mPFC and SIRT1 inhibitor limited the role of S-ketamine in reducing the depression-like behavior and increasing the BDNF level." (PMID 35664490, 2022). "To explore the upstream mechanism for SIRT1 to regulate the chronic pain-related depression-like behaviors, we analyzed the differentially expressed lncRNAs, and the novel lncRNA-84277 drew our attention." (PMID 35959106, 2022). "Given Gpx4 plays a crucial role in glutathione metabolism and the involvement of Sirt1 and Nrf2 in MDD, we next sought to examine the role of Sirt1/Nrf2/HO-1/Gpx4 pathway in EDA-related depression and anxiety by WB." (PMID 35130906, 2022). "In the chronic neuropathic pain model, the decrease of HDAC subtype sirtuin-1 (SIRT1) in the CeA increased H3K9, allowing animals to be at higher risk of emotional comorbidities, such as anxiety and depression." (PMID 35600618, 2022). "The role and possible mechanisms of SIRT1 have revealed novel therapeutic strategies for clinical treatment of depression." (PMID 35935939, 2022). "Specifically, recent studies have shown that Sirt1 plays a crucial role in depression and regulates downstream transcription factor including nuclear factor erythroid 2-related factor 2 (Nrf2) and NF-κB to prevent OS and inflammation damage." (PMID 35130906, 2022). "In our previous work, we have found that CeA SIRT1 plays a vital role in chronic pain-induced depression." (PMID 35959106, 2022). "Third, lncRNA-84277 improves SNI-induced depression-like behaviors by relieving the suppression of miR-128-3p on SIRT1." (PMID 35959106, 2022). "But those studies didn't explored the relationship between the changes of white matter and genes, the effect of the SIRT1 gene on the white matter of the brain in patients with depression is still unclear." (PMID 36177213, 2022). "Among these core targets, SIRT1, HIF1A, ESR1, VEGFA, HSP90AA1 and PTGS2 are well documented to be associated with depression." (PMID 36496991, 2022). "Previous studies and our results have confirmed that Sirt1 and Nrf2 played an important role in depression." (PMID 35130906, 2022). "SIRT1 has been suggested to be crucial to determine stress-induced anhedonia, as it enhances anxiety and depression." (PMID 35892563, 2022). "ERK2 overexpression in the hippocampus has an anti-depressant effect, whereas lower expression is associated with increased depressive symptoms, indicating the critical role of SIRT1 in regulating depression." (PMID 36583185, 2022). "In summary, our experiment demonstrated that PAP ameliorated CUMS-induced depression via AMPK/Sirt1/NF-κB/NLRP3-mediated pyroptosis." (PMID 35401226, 2022). "Resveratrol, a pharmacological activator of SIRT1, when infused bilaterally into the NA, increased depression‐ and anxiety‐like behaviours." (PMID 35875858, 2022). "Sirtuin type 1 (SIRT1) has been proved to be involved in many pathological mechanisms of depression, including glial activation, neurogenesis, circadian rhythm, inflammatory reaction and BDNF signaling." (PMID 35664490, 2022).
depression (continued). "Several studies in animal models also support the important role of SIRT1 in preventing and treating depression." (PMID 35634375, 2022). "SIRT1 participates in depression through various mechanisms, covering inflammation, BDNF signal, and neuronal excitability." (PMID 35664490, 2022). "Mechanically, lncRNA-84277 acted as a competing endogenous RNA (ceRNA) to upregulate SIRT1 expression by competitively sponging miR-128-3p, and therefore improved chronic pain-related depression-like behaviors." (PMID 35959106, 2022). "Our research results are consistent with those of the CONVERGE team, which found that the SIRT1 gene is related to depression in the Han population." (PMID 36177213, 2022). "Recently, both clinical and animal experiments have shown that SIRT1 is involved in the development of depression." (PMID 35959106, 2022). "SIRT1 has several potential roles in depression through effects on inflammation, neurogenesis, circadian rhythm and other stress-related extracellular signal-regulated kinase pathways." (PMID 33669121, 2021). "Another upregulated miR, miR-155, was also found among the included studies, and mechanistically, it was shown that it represses the expression of the silent information regulator 1 (SIRT1) gene, involved in the circadian rhythm and depression." (PMID 34685444, 2021). "From these results the authors suggested that ̇OH, due to its role in stress and SIRT1, must play an important role in depression." (PMID 34163615, 2021). "As a result of studies based on these reported functions of SIRT1, many researchers have demonstrated the relationship between SIRT1 and depression." (PMID 34065586, 2021). "One of the machinery genes, SIRT1, has been well known for its role in mental health disorders such as depression, but very few studies have examined its role as a modifier for non-additive genetic effect such as POE." (PMID 34883445, 2021). "Two loci, one of which is near the SIRT1 gene, were identified as the first robust links between genetics and depression at the whole-genome level." (PMID 34836959, 2021). "Further studies are needed to identify neuronal populations and neural circuits mediating sex difference in SIRT1 action on depression-related behaviors." (PMID 30705425, 2020). "Resveratrol treatment enhanced neurogenesis, upregulated Sirt1, and inhibited NF-kB activation ameliorating depression-like behaviors." (PMID 33292508, 2020). "Our findings suggest that SIRT1 in forebrain excitatory neurons functions as an important regulator of depression-related behaviors and a modulator of synaptic transmission and excitability of mPFC pyramidal neurons." (PMID 30705425, 2020). "Given the important role of SIRT1 gene in depression and the down-regulation of SIRT1 under CUMS, we further examined if SIRT1 expression is affected by miR-124." (PMID 31431514, 2019). "We also demonstrated that ectopic expression of SIRT1 mediated by lentiviruses was efficient in attenuating CUMS induced depression-like behaviors in mice." (PMID 31431514, 2019). "Recent studies using animal models of depression suggested that dysregulation in sirtuin 1 (SIRT1) gene expression plays an important role in the depression-like behaviors." (PMID 31431514, 2019). "A number of signaling pathways, including Akt/GSK3β signaling pathway, mTOR signaling, etc. are found to be mediated by SIRT1, posing SIRT1 as a potential mediator of neuron growth and development of depression-like behaviors." (PMID 31431514, 2019). "Recently, it has been found that Sirt1 protein expression and functional activity in a mouse model of depression have a shift in the rhythm due to chronic stress exposure." (PMID 29643977, 2018). "Recent studies using animal models of depression also found that dysregulation of Sirt1 signaling has a critical role in depression-like behaviors." (PMID 29643977, 2018).
depression (continued). "Recently, a genetic study has received considerable attention for depression and found that Sirt1 is a potential gene target." (PMID 29643977, 2018). "In a mouse model of depression, SIRT1 expression was increased in the nucleus accumbens (NAc), a brain region associated with reward and motivation." (PMID 30416425, 2018). "Intra-NAc bilateral infusion of the SIRT1 agonist resveratrol in mice with viral-mediated overexpression of SIRT1 increased anxiety- and depression-like behavior in the open field, elevated plus maze, and forced swim tests." (PMID 30416425, 2018). "Further, it has been shown that Sirt1 expression in the peripheral blood from individuals with depression is significantly less than those in healthy subjects." (PMID 29643977, 2018). "Later studies demonstrated decreased expression of SIRT1 in subjects with major depressive disorder compared to controls." (PMID 30416425, 2018). "SIRT1 is a target of many types of miRNAs, although miRNA-mediated regulation of SIRT1 in depression has not been fully understood." (PMID 30271325, 2018). "Sirt1 belongs to the III HDACs that has been linked to various pathophysiological conditions, including depression." (PMID 29643977, 2018). "Resveratrol, an antidepressant known to improve hyperanxiety status and attenuate depression-like behaviors, was demonstrated to activate SIRT1." (PMID 30482883, 2018). "In an animal model of depression, treatment with resveratrol that is a well-known Sirt1 activator can promote antidepressant effects in Wistar-Kyoto (WKY) rats." (PMID 29643977, 2018). "Sirt1, an NAD+-dependent deacetylase, has been extensively studied for its connection to depression, but the specific role of Sirt1 remains controversial." (PMID 29643977, 2018). "In conclusion, our data provide the first evidence that RSV-induced activation of Sirt1 reverses LPS-induced depression-like behaviors by enhancing neurogenesis." (PMID 27517628, 2016). "Taken together, these data indicated that RSV-induced Sirt1 activation counteracts LPS-induced depression-like behaviors via a neurogenic mechanism." (PMID 27517628, 2016). "Overall, these findings are consistent with SIRT1 having a critical function in establishing the ESI-induced depression-like phenotype." (PMID 26327687, 2015). "We also performed a pilot study in humans, in which the blood levels of SIRT1 correlated significantly with the severity of symptoms in major depression patients, especially in those who received less parental care during childhood." (PMID 26327687, 2015). "Our results suggest causal relations between microglial SIRT1 or FOXO1 and therapeutic activity of UB in depression‐related behaviors and/or cytotoxicity and provide more evidence to expand the powerful actions of SIRT1 in the pathology and treatment of depression." (PMID 40237232, 2025). "Sirt1, recognized for its protective roles, is correlated with anxiety and depression." (PMID 41317200, 2025). "The tissue- and context-dependent effects of SIRT1 modulation exemplify this complexity: SIRT1 inhibition may be beneficial in hippocampal tissue for anxiety and depression but could have different consequences in cancer cells or cardiovascular tissue." (PMID 41304625, 2025). "In the current investigation, we observed that UB exerted efficient therapeutic activities on depression‐like behaviors, suppressed microglia activation and neuroinflammation, balanced M1/M2 polarization, and restored the abnormal levels of SIRT1 and FOXO1 in the hippocampus." (PMID 40237232, 2025). "Studies of MDD patients and animal models have revealed the essential role of SIRT1 in depression." (PMID 40237232, 2025). "Two studies showed lower Sirt1 blood levels in patients with depression versus controls." (PMID 38396638, 2024). "Additionally, the selective inhibition of SIRT1 attenuated the therapeutic effect of PF on depression." (PMID 39684254, 2024).
depression (continued). "Additionally, hippocampal SIRT1 signaling mediates anxiety- and depression-like behaviors in rat models of sleep deprivation and the rat chronic restraint stress model." (PMID 39744519, 2024). "Hippocampal Sirtuin 1 (SIRT1) signaling mediates anxiety- and depression-like behavior." (PMID 39744519, 2024). "So far, there have been many studies linking SIRT1 to depression." (PMID 39684318, 2024). "Pharmacological inhibition of SIRT1 in the NAc reduces anxiety- and depression-like behaviors." (PMID 39275174, 2024). "Finally, we investigated the effects of pharmacological activation of SIRT1 on anxiety- and depression-like behaviors, the SIRT1/PGC-1α/NRF1/TFAM signaling axis, and mitochondrial biogenesis." (PMID 39744519, 2024). "The mechanism of PF for depression was assessed by the SIRT1 selective inhibitor EX-527." (PMID 39684254, 2024). "In summary, total ginsenosides may regulate the AMPK signaling pathway and activate the sirtuin 1 (SIRT1) peroxisome proliferator-activated receptor-gamma coactivator 1-alpha (PGC-1α) pathway to have therapeutic effects on depression." (PMID 39684318, 2024). "Both ERα and SIRT1 antagonists can reverse the effects of E2, suggesting that E2 may protect aging female mice from depression through the E2/ERα/SIRT1/NF-κB signaling pathway." (PMID 38898454, 2024). "It is thought that SIRT2 may collaborate with SIRT1 in the pro-inflammatory cascade in depression, and inhibition of SIRT2 may aid in ameliorating downstream changes in MDD." (PMID 39404407, 2024). "Furthermore, our study highlighted the role of relatively new markers for neuroinflammation by focusing on the roles of ICAM-1, SIRT1 and NO in psychiatric disorders, namely stress, anxiety and depression." (PMID 38396638, 2024). "Depression is closely related to neurological dysfunction, and the neuroprotective effect of SIRT1 may help alleviate the occurrence and development of depression." (PMID 39612426, 2024). "The anti-aging gene Sirtuin 1 (SIRT1) was confirmed to be a depression and stroke-related gene." (PMID 38384936, 2024). "Similarly, SRT2104, a selective SIRT1 activator, has been assessed in clinical trials for use as an anti-inflammatory agent to target depression and PTSD." (PMID 39404407, 2024). "To further clarify whether the mechanism of TGGR regulating depression is related to the AMPK/SIRT1 signaling pathway, we used immunohistochemistry, immunoimprinting, and RT-qPCR to detect the protein expression level of this pathway." (PMID 39684318, 2024). "Moreover, the SirT1 pathway is involved in the neuroprotection, depression, and anxiety in models of PD." (PMID 38473763, 2024). "Further evidence points to a positive correlation between BDNF levels and SIRT1 activation, where the co-occurrence promotes cognitive function and lessens the impact of detrimental effects such as toxins, sleep debt, or models of depression and schizophrenia." (PMID 39404407, 2024). "However, further investigation is essential to explore the potential link between SIRT1 activity modulation and anxiety- and depression-like behaviors mediated by mitochondrial mitophagy." (PMID 38916735, 2024). "In addition, SIRT1 appears to be involved in the development of dependence, anxiety, and depression, which are clinical dimensions present in AN." (PMID 37373917, 2023). "The SIRT1 expression in the CA1 region of the hippocampus plays a role in promoting depression." (PMID 37239191, 2023). "An animal experiment showed that knock-out of SIRT1 in the hippocampus of mice resulted in memory impairment, reduced secretion of neurons, decreased dendritic complexity, and perturbed synaptic plasticity in the mice, leading to depression-like behaviors." (PMID 37239191, 2023). "Similarly, the alleviating effects of neuroinflammation and depression were obtained through activating the Sirt1/NF-κB signaling pathway by Polydatin in lipopolysaccharide-treated mice." (PMID 37273278, 2023).